IL4 (interleukin 4)
Diseases named in the same sentence as IL4 in open-access papers (continued):
Sharing a sentence is not in itself a finding about the gene and the disease.
infection (continued). "Th1 CD4+ cells confer immunity to infection by intracellular pathogens through production of effector cytokines IFN-γ, Il-12, TNF, and IL-2, while Th2 CD4+ cells promote the clearance of multicellular helminths and ectoparasites by producing IL-4, IL-5 and IL-10." (PMID 22685452, 2012). "However, the absence of differences in serum levels of IL-4, IL-12, IFNγ and GM-CSF after infection does not exclude the possibility that they are involved in the local response to L. tropica." (PMID 22679519, 2012). "Although we did not detect changes in the profile of IFN-γ and IL-4 against the egg antigen, the treated animals sacrificed at 60 days following infection showed changes on morphological aspects of the hepatic parenchyma of mice infected and treated with LPSF-PT05-PEG, at a dose of 100 mg/kg." (PMID 22623908, 2012). "For comparison, we also evaluated mRNA levels of the canonical Th2 cytokine gene IL-4 in NFATp−/− and wild-type mice, since mice deficient in IL-4, including mice of the BALB/c background, do not display decreased survival following MTb infection." (PMID 22844476, 2012). "However, IL13RA, IL3RA, IL4, STAT1, STAT4 were down-regulated at this time point of infection." (PMID 21439068, 2011). "CD4+ T cell specific (LckcreIL-4Rα−/lox) IL-4Rα−/− mice are more resistant than global IL-4Rα−/− mice to infection with L. major, indicating that in the absence of a polarized Th2 response, there is a role for an IL-4/IL-13 responsive non-CD4+ T cell in early resistance to infection." (PMID 21245915, 2011). "To conclude in this study utilising tissue specific IL-4Rα−/− mice we demonstrate that upon infection with L. mexicana initial lesion growth is dependent on a non-CD4+ T cell population responsive to IL-4/IL-13, while progressive infection is dependent on CD4+ T cells responsive to IL-4." (PMID 21245915, 2011). "Moreover, the injection of CFA did not affect the course of infection in IL-4-deficient mice, suggesting the exacerbation of PCM after inoculation of CFA was mediated by IL-4 and not IL-10." (PMID 21731741, 2011). "In response to infection (LCL-Vacc), all cytokines, with exception of IFN-γ, were detected in all clones and, similarly to the response to low antigen concentration (peptide at 5 ng/ml), GM-CSF, TNF-α, IL-13 and IL4 were detected at 48 hours at significantly higher levels than those at 6 hours." (PMID 21931646, 2011). "Low levels of IL-4 were produced by lymph node cells isolated from animals inoculated with LTCP15171(S) three weeks post-infection and stimulated with live parasites, but no IL-4 was detected in the lymph node cells from animals inoculated with LTCP393(R) at this time point." (PMID 21390155, 2011). "Specific CTL are critical in the recovery from infection and the clearance of HSV-2, and the Th2 immune response against HSV-2 is also protective, the remarkably increased CTL activity and IL-4 production in the MEAP group may indicated that the MEAP has a higher degree of protection effect." (PMID 21575169, 2011). "In addition, Balb/c mice had IL-4 by day 28 post-infection, whereas Balb/c controls and C57Bl/6 mice (infected and control) did not produce detectable IL-4 in their serum (data not shown)." (PMID 20625554, 2010). "Following infection with the Ts strain (cell-adapted virus) these cytokine transcripts were up-regulated at 5 days post-infection (dpi), 2- and 13-fold respectively (P < 0.05), while the expression levels of IL-2 and IL-4 were not significantly different (P > 0.05)." (PMID 21143846, 2010). "As expected, a classical Th2 cytokine profile with up-regulation of IL-5, IL-13 and to a lesser extent of IL-4, but with no changes in IFNγ transcript levels, was observed in these pooled samples with expression levels peaking after the third immunising infection and immediately after challenge." (PMID 20950493, 2010).
infection (continued). "Moreover, the granzyme b, nk-lysin, ifnγ, il4 and il10 mRNA levels in early skin-draining lymph nodes of immunized pigs were higher than those in pigs with non-irradiated cercariae infection." (PMID 20976218, 2010). "Recently we demonstrated that pre-patent schistosome infection and infections with either male or female worms alone that preclude the possibility of egg production, also induce type 2 responses, characterized by induction of CD4+ T cells and basophils that produce IL-4 in response to worm antigens." (PMID 21078176, 2010). "Consistent with previous findings, our experiments showed that the dose of worms administered, irrespective of the infection regime, was positively correlated with the concentration of IL4 and IL13 produced by parasite antigen-stimulated MLNs, the concentration of anti-S." (PMID 18575588, 2008). "However, at 72 hours post-infection, the expression of IL-17, IFN-γ, T-bet, RORγt, and IL-6 genes was markedly reduced in the Pm_OMVs-infected group compared to the Pm group (P < 0.01), whereas the expression levels of TGF-β, GATA-3, IL-4, and FoxP3 were significantly increased (P < 0.01)." (PMID 41306977, 2025). "However, ZNFX1 did not appear to affect IL-4 and IL-10 expression in the early stages of infection." (PMID 38016036, 2024). "However, we could not detect any IL-4 or IL-13 cytokine release from mLN Treg cells after secondary infection while Treg cells of both genotypes released equivalent amounts of IL-10 suggesting fully functional Treg cells in RelBΔDC mice." (PMID 39443450, 2024). "In addition, after infection with PEDV-CV777 strains, it was found that the secretion levels of transforming growth factor (TGF)-β and IFN-α were significantly higher in B cells from nursery piglets at 48 hpi and those of IL-4 significantly increased from nursery piglets at 24 hpi." (PMID 38585694, 2024). "As there is evidence for increased IL-4 and IL-10 responses in the airways of RSV-infected patients, the reduced blood transcriptomic markers could be due to a local response to RSV, but with limited evidence for immune cell signalling in the airways during infection, this is still unknown." (PMID 35406717, 2022). "It meant that USA300 infection may not affect the expression of IL‐4 and IL‐10 in the mPFC." (PMID 35977050, 2022). "However, the study also showed that the mRNA expression and protein level of IL-4 in lung homogenates did not increase during the course of infection compared to the Control WT mice, thus indicating that Ch. pneumoniae infection during early life does not increase the levels of IL-4." (PMID 34226412, 2021). "However, none of the wt BoHV-1 infection groups were detectable in IL-4 after infection." (PMID 34822626, 2021). "CF mice exposed to B. pseudohinzii displayed a significant decline in IL-4, and a non-significant reduction in IL-2 serum levels, both of which serve as the predominate regulators of T-cell proliferation and B-cell activation during an adaptive immune response to infection." (PMID 34475490, 2021). "Additionally, our pathway analysis revealed seven genes, IL-4, IFNγ, TLR4, CXCL8, IL-18, CSF2 and TNFα, are involved in the morphological and behavioral changes of macrophages, monocytes, granulocytes, and dendritic cells (DCs) and their recruitment into infection sites." (PMID 34753991, 2021). "This is in contrast to worm (Trichinella spiralis) infection, during which IL-13, but not IL-4, is affecting murine goblet cell proliferation, pointing to that the combined effect of the pathogens and the immune system determines the mucin/mucus changes during infection." (PMID 30665337, 2019). "Hence the observed lack of significant elevation in serum IL-4 levels across all the treatment groups was attributed to the study being centred around a primary infection as opposed to a secondary infection (or re-infection) where this cytokine (IL-4) reportedly partakes in the immune response(s)." (PMID 31856836, 2019).
infection (continued). "Levels of IL-4, an indicator of humoral immunity, which may have been beneficial in this case, were notably decreased upon treatment with atorvastatin in the presence or absence of infection." (PMID 31406240, 2019). "However, because Mφ alternative activation can occur independently of IL4R via FcR ligation or other polarising signals such as IL-33, we do not rule out a role for Mφ alternative activation signals being triggered by non-lymphocyte, IL-4 responsive cell types in our infection system." (PMID 29547639, 2018). "Furthermore, the dose of IL-4 injected locally may not correspond to cytokine levels present at the site of infection in L. major-infected C57BL/6 mice." (PMID 29067025, 2017). "In addition to the cell migration, the infection of microglia with P. gingivalis significantly increased the mRNA expression of proinflammatory mediators, including IL-6, TNF-α, and iNOS, without affecting the mRNA expression of anti-inflammatory mediators, including IL-10, arginase-1 and IL-4." (PMID 28924232, 2017). "This suggests that in the absence of anti-inflammatory cytokines (such as IL-10, IL-13, and IL-4), Th1/Th17 cells proliferate simultaneously and are responsible for parasite elimination, although neutrophil migration, and its role in this situation (3.5 weeks post-infection), was not assessed." (PMID 29163510, 2017). "This reduction in inflammation was associated with lower IFN-γ and increased IL-4 and IL-10 levels (data not shown), which suggests that WGA-Fc therapy may both result in a more rapid resolution of the infection and diminished sequelae of disease, such as complications of fibrosis." (PMID 28939893, 2017). "Consistent with the leukocyte responses, we observed no significant increases in IL-4 or IL-13 gene expression in the livers or intestines (not shown) of IL-4Rαflox/ΔLysMCre mice when compared with expression in IL-4Rαflox/Δ littermate controls 9 and 16 weeks post-infection." (PMID 25211233, 2014). "However, in the absence of IL-4, or IL-4Rα, the infection is acutely lethal." (PMID 25144366, 2014). "This difference may not be solely attributed to the genetic background of the mice as Itk−/− on a BALB/c background have also been reported to significantly reduce IL-4 production in the absence of a significant effect on IFNγ, however this was following infection with L.major." (PMID 25250764, 2014). "Thus, one of the reasons for the asymptomatic evolution of the infection observed in those dogs despite the high parasite load in bone marrow, liver, and spleen could have been related with the no expression IL-4 by these organs." (PMID 21845197, 2012). "Finally, the ratio of IL-4 to IFN-γ or the IL-4 antagonistic splice variant, IL-4δ2, appears to be correlated with clinical status and in particular, with TB-related pathology rather than of infection." (PMID 21253484, 2011). "In addition, cytokines such as IL-4 produced during infection could mediate arginase-1 induction in infected and noninfected cells, and this could also complicate the results." (PMID 21931552, 2011). "On the other hand, IL-4 is able to induce production of IL-12p70 in murine and human DC in vitro and to promote a protective Th1 immune response in susceptible BALB/c mice but only when administered during the first 8 h of infection, and not if given for a prolonged period of time." (PMID 20442861, 2010). "IL-4, IL-10, and TNF remained below the detection limit in all experimental groups, regardless of infection status (data not shown)." (PMID 41415569, 2025). "IL-4, IL-10, and TNF-α levels were below the detection limit in all experimental conditions, regardless of infection status (data not shown)." (PMID 41415569, 2025). "Restimulation of mesenteric lymph node (mLN) cells 21 days post-infection (p.i.)with anti-CD3/CD28 induces the production of type-2 cytokines, such as IL-4, IL-5, and IL-13, in cells derived from WT mice but not in A20myel-KO mLN cells." (PMID 38680500, 2024).
infection (continued). "While most genes showed no significant change in expression upon infection, a few patterns emerged: TBX21 and IL-4 were slightly under-expressed in infected cells, while IL-33 was slightly over-expressed." (PMID 39273061, 2024). "Early after infection (day 4 PI), plasma levels of IFN-γ, TNF-α, IL-3, IL-17, IL-1β, and IL-4 were increased in baso IL-18R (−) mice but not in basophil-depleted mice." (PMID 38780542, 2024). "Although the fungal burden in the lung tissue was not significantly different among the groups, the levels of IL-4 and IL-5 were strikingly increased in the LincR-PPP2R5C KO mice at 14 days post infection." (PMID 39287443, 2024). "The fact that on this occasion IL4 levels did not go back to normal levels is not well understood and may require further exploration in the future, as it may explain the reason why there was a negative association between IL4 and the CSDD in the infection group." (PMID 37762523, 2023). "Despite that, IL-4 and IL-10 knockout mice have impaired IL12 production and Th1 response and are not able to resolve infection by L. amazonensis or L. major." (PMID 37000792, 2023). "In comparison with control, non-treated mice, blocking IDO produced a decrease of bacilli burdens at day 60 post-infection, without significant difference in IFN-γ, TNF-α, and IL-4 expression." (PMID 37284503, 2023). "At 4 weeks post infection both groups produced increased levels of IFN-γ, IL-4, IL-10, and TNF-α from splenic cells that were not statistically different between the groups, however, the trend was for higher mean levels in the WT-inoculated animals." (PMID 37185599, 2023). "During PDTB, the Th profile was predominantly mono-cytokine and polyfunctional, with populations of IL-4+ or IL-10+ cells most abundant, consistent with their increase during PDTB irrespective of infection." (PMID 37898618, 2023). "It was seen that early in infection NKT cells migrated to the B cell border in the mediastinal LN and provided non-cognate B cell help via the local production of IL-4." (PMID 35260653, 2022). "In line with a reduced ability to produce alternatively activated macrophages, infection-induced levels of RELMα were reduced in the BAL of Ptpn2-LysMCre mice, while IL-4 and IL-13 were not affected and IL-6 and IL-17 were elevated." (PMID 34420044, 2022). "This occurred in several experiments with different sets of cows, with a decrease in average relative gene expression of IL-4 from 500 for PWM-stimulated cells to an average of 2 for MPS-stimulated cells, regardless of infection status of cows." (PMID 36477266, 2022). "Among children without infection, PBMCs stimulated with SEA produced greater IL-12 (P = 0.03) and with SWAP produced less IL-4 (P = 0.01) in the maternal PZQ group compared to placebo." (PMID 33861768, 2021). "Antigenic-derived proliferation of CD4+ T cells with rFhCB3 and rFhCL2 failed to produce IL-4 and to significantly enhance IFN-γ production during early and late stage of the infection." (PMID 34215335, 2021). "Plasma levels of six cytokines (IL-2, IL-3, IL-4, IL-7 and VEGF) were not significantly altered by Kp-1705 infection nor were they affected by MTD12813 treatment." (PMID 34873199, 2021). "Elevated mRNA levels of Th1 cytokines were observed after the 1st week post-infection and, later on, as was a low level of IL-12 and IFN-γ transcript, while the Th2 cytokine IL-4 did not elevate in L. donovani-infected hamsters." (PMID 33680991, 2021). "PDGFRβ correlated negatively in BSIII–IV and positively in BSV–VI with several cytokines (IL-10, IL-12, IL-13, IL-2, IL-4 and TNF-α) but only in the absence of infection." (PMID 33723589, 2021). "For having remained below the technique detection limit, we did not interpret the following values: uninfected mice, IL-2, IL-4, IL-10, and IL-17 values of infected mice, as well as IFN-γ, TNF-α, and IL-6 levels at the infection times from 6 to 240 h." (PMID 34660334, 2021).
infection (continued). "Studies on L. donovani and L. infantum infections in mice and humans suggest that control of infection was independent of the Th1 and Th2 cytokine differential production (IFN-γ/IL-4 balance)." (PMID 34036108, 2021). "Infection by S. oralis WT or spxB KO, or exposure to H2O2 did not stimulate IL-4 production from the RBL-2H3 cells, whereas PMA + ionomycin induced its production (left)." (PMID 32302339, 2020). "Infection resulted in an increase in antigen-specific cell proliferation, IFN-γ and IL-10 production by PBMC, but not IL-4 or IL-17A." (PMID 32487248, 2020). "Neither IFN-γ nor IL-4 were detected in the PA and AD-MSC + PA groups, indicating resolution of infection." (PMID 32867857, 2020). "The cells were incubated with IL-4, IFN- γ, LPS, P3C4, or ArtinM for 24 h previously the addition of C. gattii, and after 5 h of in vitro infection the non-adherent yeasts were removed." (PMID 33304649, 2020). "This suggests that innate sources of IL‐4, such as basophils, eosinophils and ILC2 are unlikely to be capable of inducing the proliferation of macrophages during infection." (PMID 32145033, 2020). "In the absence of infection, addition of IFN-γ and TNF-α trended towards decreasing the amount of incorporated label, IL-13 had no apparent effect, while IL-4 increased the mucin production and transport speed en route exocytosis (p < 0.001)." (PMID 30665337, 2019). "However, differential exposure of myeloid cells to IL-4 may not be decisive in pathogenesis, since similar mortality, bacterial burden, histopathology and iNOS expression were observed after infection of wildtype or myeloid-specific IL-4Ralpha knockout mice with H37Rv or HN87846." (PMID 31882653, 2019). "We further demonstrate both in vivo and in vitro that IL-4/IL-13 enhances EBOV GP specific entry, as rVSV/G infection of mice and pmacs were not altered by these cytokines." (PMID 31825972, 2019). "Similar to WT mice, in the CNS of Rag1−/− mice IFN-α1, IFN-β, TNF, IL-1α, IL-1β, IL-6, and IFN-γ mRNA levels increased following i.c. infection with ZIKV, and IL-2, IL-3, IL-4, and IL-5 mRNA was not detectable (data not shown)." (PMID 31511023, 2019). "On the other hand, if the parasite load of the IL-4-stimulated C3H/He macrophages is compared to non-stimulated BALB/c macrophages, there is an inversion 48 and 96 hours after infection." (PMID 31856207, 2019). "We found that IL-4/IL-13-stimulated macrophages were more robustly infected by rVSV/EBOV GP as compared to non-polarized controls, with a 3-4-fold increase in infection observed." (PMID 31825972, 2019). "The enhanced dermal inflammation early in infection in the absence of CCL7 was characterized by elevated neutrophils, IL-4, and IL-17." (PMID 30671055, 2018). "After the double infection, the DRI group had no detectable IL-4, and nor did the HBC group, but the rest of the interventions induced the production of this cytokine, with the SYN group being the one with the highest production." (PMID 29942312, 2018). "In Hsd11b1Del/Del mice, only IL-4 and TNF-α were significantly increased in response to the infection (respectively, p = 0.0061, 0.0061), and non-significant trends were noted for IFN-γ, IL-5 and IL-6 (respectively, p = 0.103, 0.109, 0.103)." (PMID 29062028, 2017). "First, to ensure that digestion of the ear would not impact IL-4 detection, KN2/4get mice, all on the C57BL/6 genetic background, were treated with anti-IFNγ and anti-IL-12 mAbs at the onset of infection to induce Th2 cell differentiation." (PMID 29067025, 2017). "In terms of cytokine expression, compound-6 treated mice had significantly higher expression of IL-6 (lung and brain), IL-4 (lung and brain), IFN-γ (lung and brain), TNF-α, IL-β1and IL-12 (lung) when compared to control group (without infection)." (PMID 29133871, 2017).